CCR4 (C-C motif chemokine receptor 4)
Diseases named in the same sentence as CCR4 in open-access papers (continued):
Sharing a sentence is not in itself a finding about the gene and the disease.
tumor (continued). "An additional reason for decreased functionality of multiple-transduced cells may be a synergistic PD-1 induction dependent on different chemokine receptors: CCR6 showed increased PD-1 expression in the tumor and CCR4 in draining lymph nodes." (PMID 37301772, 2023). "Interestingly, further imaging analysis identified TAMs-CM-T treatment led to the aggregation of calcium in ER, which was impaired by the pretreatment of tumor cells with CCR4 antagonist." (PMID 37658050, 2023). "Moreover, the hypoxia induced by target drug can elevate the level of GSF1, HIF, and CCR4 to effect M2 lead to tumor progress." (PMID 37809069, 2023). "Moreover, treatment with rCCL2 increased paxillin phosphorylation in tumor cells (mean: 3.13), while CCR4 inhibition decreased p-paxillin amounts (mean: 1.06)." (PMID 37607005, 2023). "Besides CCR2, CCR4 has been reviewed and recognized as a highly relevant receptor for immunological tumor infiltration." (PMID 37371612, 2023). "have shown that tumor-infiltrating CD4+Treg express CCR4 in lymphoma and gastric cancer." (PMID 38250084, 2023). "The third group received CCR4 inhibition two weeks after tumor injection." (PMID 37371612, 2023). "Therefore, new targeted therapies have been developed targeting surface molecules expressed on the surface of tumor cells, such as CCR4, HDACs, CD30, and CD25, CD52, specific for MF and SS." (PMID 37259456, 2023). "Hence, on average, CCR4−/− mice’s tumors contained 3753 ± 2557 less CD19+ B lymphocytes per 1 × 105 tumor cells than the tumors of WT mice, corresponding to a relative reduction of 65%." (PMID 37371612, 2023). "It has been suggested that CC chemokine receptor 4 (CCR4) mediated Treg recruitment into the TME, antagonism of which could suppress the frequency of CCR4 reduced Tregs and potentiated anti-tumor efficacy of ICIs." (PMID 37386520, 2023). "C-C Motif Chemokine Receptor 4 (CCR4) inhibitors, which mediate tumor trafficking of regulatory T cells (Tregs), lead to decreased Treg frequency and increased antitumor activity; however, CCR4 inhibitors are used in combination with CPI to improve antitumor efficacy." (PMID 37197420, 2023). "In a recent study, macrophage-derived CCL17 drove tumor invasion by acting on the CCL17/CCR4/mTORC1 pathway, suggesting that chemokines secreted by non-tumor cells may positively favor the invasiveness of PitNETs." (PMID 37958702, 2023). "Tumor Treg express chemokine receptor 4 (CCR4), while its ligand CCL12 (chemokine ligand 12) is secreted by GBM that could explain infiltration of tumor by Treg." (PMID 36960410, 2023). "Moreover, ectopic CCR4 expression in CD8 T cells enhances their tumor migration and therapeutic efficacy in ACT." (PMID 36045586, 2023). "Less common immunosuppressive cell types in human HCC consist of B cell population expressing PD-1, Th17 cells, CD4+ T cells expressing CCR4 and CCR6, CD14+ DCs expressing CTLA-4 and PD-1, tumor-associated neutrophils, tumor-associated fibroblasts, and type-II T helper cells (Th2)." (PMID 36845131, 2023). "CCR4 is present in the neoplastic cells of most patients with this type of tumor." (PMID 37259456, 2023). "A phase I study (NCT02476123) showed that combining nivolumab, with mogamulizumab (a Treg-depleting anti-CCR4 antibody) provided an acceptable safety profile and anti-tumor activity, with populations of effector Tregs reduced and CD8+ T cells in TILs increased." (PMID 37386520, 2023). "Disrupting CCR4 or paxillin activity limited NI and dampened tumor size and tumor innervation." (PMID 37607005, 2023). "Chemokines, the ligands of chemokine receptors, are a family of interactive chemotactic cytokines, used to coordinate cell migration and home in the body CCL22 is the ligand of CCR4 transmembrane protein, which is mostly produced by tumor cells and tumor-infiltrating macrophages." (PMID 35176085, 2022).
tumor (continued). "We reasoned that reducing CCR4 expression could aid in controlling these immunosuppressive pro-tumor Tregs and hence slow tumor growth." (PMID 35222362, 2022). "The enrichment of Tregs in the tumor seems to be driven by the expression of the chemokine receptors CCR4 and CCR7 that drives their migration and also the chemo attractants such as monocyte chemotactic protein-1 (MCP-1) also known as CCL2 and C-C chemokine ligand 22 (CCL22)." (PMID 36338731, 2022). "Three tumor antigens (CCR4, TMCO1, and SPACA4) related to APCs infiltration and prognosis in HNSCC were identified, and it is expected that these genes might become candidate antigens for an mRNA vaccine." (PMID 36671475, 2022). "CCR4 could enhance anti-tumor immunity, mainly by targeting and blocking the infiltration of regulatory T cells (Tregs)into the tumor microenvironment and inhibiting the stability of the TIL-Treg pool." (PMID 36159990, 2022). "Similarly, anti-CCR4 antibody selectively depletes intratumoral Treg cells, promoting anti-tumor T cell responses." (PMID 35359918, 2022). "CCR4+ Tregs have a higher frequency distribution in the tumor site, but CCR4- Tregs dominate in the peripheral circulation, implying that Tregs that gain CCR4 expression in the peripheral circulation travel to the tumor site." (PMID 35222362, 2022). "We also investigated the specific association between FAM46C expression and chemokines and their receptors in pan-cancer and found that FAM46C expression was positively correlated with immune chemokines (CXCL9 and CXCL13) and immune chemokine receptors (CCR2 and CCR4) in most tumours (all p < 0.01)." (PMID 35222533, 2022). "CCR4 is also expressed in the tumor cells of most ATL patients." (PMID 36555280, 2022). "Therefore, CCR4+CD8+ TILs should be protected from ADCC by mogamulizumab to augment anti-tumor immunity." (PMID 36522365, 2022). "Anti-CCR4 mAb could be an appropriate treatment for a variety of malignancies, not only because it kills CCR4-expressing tumor cells directly, but also because it overcomes Treg cells’ suppressive influence on the host immune response." (PMID 35222362, 2022). "Additionally, it has been evident that engineered co-expression of CAR and C-C chemokine receptor 4 (CCR4) by effector T cells can result in enhanced tumor-site trafficking and tumoricidal cytotoxicity." (PMID 35634281, 2022). "Together, these results suggested that CCL2-CCR4 signaling played an essential role in the local invasion and metastasis of HNSCC, and CCR4 might serve as a potential therapeutic molecular target by inhibiting tumor invasion metastasis." (PMID 35177591, 2022). "Furthermore, depleting CCR4+ Tregs seems to reduce the tumor burden both as a standalone therapy and in combination with checkpoint blockade in certain tumor settings." (PMID 36248808, 2022). "Our findings revealed a novel role for FOXP3 in the regulation of CCR4 expression in tumor-infiltrating Tregs and gave a molecular insight as to how immunosuppressive Tregs infiltrate into the TME, allowing us to disrupt the pathway implicated and increase cancer immunity." (PMID 35222362, 2022). "This infiltrating CCR4+ Treg expands in the tumor site, mounting the tumor immune escape." (PMID 35222362, 2022). "Third, CCR4 blockade may reduce the accumulation of Tregs in the tumor sites and improve therapeutic benefits in different types of cancers." (PMID 36246629, 2022). "Therefore, in this study, to examine and confirm the localization of CCR4+CD8+ T-cells in the tumor microenvironment, multifluorescence immunohistochemistry (MF-IHC) was performed." (PMID 36522365, 2022). "Similarly, investigators firstly correlated CAR-T cells co-expressing CCR2b/CCR4 exhibited tumor total clearance in vivo to their higher tumor tissue homing activity." (PMID 36466874, 2022).
tumor (continued). "The translational in vivo tumor model suggested that altering the expression of either CCR4 or FOXP3 in cancer patients could improve the efficacy of chemotherapy or immunotherapy." (PMID 35222362, 2022). "Anti-CCR4 mAbs exert cytotoxic action on both CCR4-positive tumor cells and Tregs." (PMID 33628584, 2021). "All these results demonstrate that different chemokine receptor/ligand pairs contribute to Treg recruitment at the tumor site, according to specific contexts; however, CCR4 and CCR8 appear as the most selectively expressed on TA-Tregs compared to Tregs from the periphery or the healthy tissues." (PMID 33924428, 2021). "Although no direct evidence has been found yet in tumors, CD26-mediated cleavage of CCL22 could affect its primary function as CCR4+ Treg recruiter and as such contribute to a tumor unfriendly environment." (PMID 34503058, 2021). "It was found that in 2 patients, > 10% of the CD56-positive tumor cells were CCR4-positive." (PMID 33628584, 2021). "Accordingly, CCR4-targeted cancer immunotherapy aiming at Treg depletion may also suppress anti-tumor immunity by depleting other T cell subsets including Th17 cells." (PMID 34885241, 2021). "CCR4 could, furthermore, be a strategy adaptable to the context of PBTs, as it seems to play a critical role in tumor progression." (PMID 34771608, 2021). "NK cells secrete CCL22 to recruit Tregs via CCR4 within the tumor and it may intensify the level of immune-inhibition." (PMID 34177887, 2021). "Additionally, Tregs and tumor cells as well as the long half-life of anti-CCR4 mAbs favor induction of antitumor effector T cells." (PMID 33628584, 2021). "Th2 cells, characterized as CD45+CD4+CCR4+, were decreased at the tumour site upon ITPP treatment." (PMID 33624446, 2021). "CCR4 antagonism may therefore prevent Treg tumor infiltration and increase the antitumoral response." (PMID 33669094, 2021). "Thus, blocking CCR4 by mogamulizumab has been regarded as a promising strategy to enhance tumor-specific immune responses by depleting Treg cells." (PMID 34885241, 2021). "Although evidence that CD26 downregulation preserved the intact CCL22 isoform was not provided, preservation of intact CCL22 in this setting could contribute to CCR4+ SS tumor cell accumulation in the skin." (PMID 34503058, 2021). "CCR4 expressed by Treg cells can suppress anti-tumor immune response." (PMID 33854960, 2021). "Thus, immunofluorescence staining of the chemokine receptors CXCR3 and CCR4 confirms the low Th1:Th2 ratio and thereby the Th2-skewing of the immune landscape in tumor stroma and TLS." (PMID 34868011, 2021). "Moreover, CCL17 released from M2-like TAMs enhances tumor invasion of PAs via the CCL17/CCR4/mTORC1 axis." (PMID 33664865, 2021). "Humanized mice have been utilized in OC: a model developed with CAR-T cells demonstrated complete tumor regression, and monoclonal antibody immunotherapy in a separate model showed that anti-CCR4 enhanced the anti-tumor immune response by hindering the infiltration of Tregs into the TME." (PMID 33918476, 2021). "CCR4 plays a crucial role in Tregs migration and infiltration into tumor site." (PMID 34806028, 2021). "Blocking the CCL22-mediated recruitment of CCR4+ Tregs may provide a potential strategy to control tumor growth." (PMID 33710805, 2021). "C‐C chemokine receptor 4 (CCR4) is expressed by tumor cells of most ATL patients." (PMID 33022137, 2021). "Furthermore, anti-CCR4 monoclonal antibodies (mAbs) exert cytotoxic actions on both CCR4+ tumor cells and regulatory T cells." (PMID 33628584, 2021). "We found that the expression of FOXP3 and CCR4, and the percentage of CD4+FOXP3+ and FOXP3+CCR4+ Tregs chemoattracted to the tumor sites were significantly downregulated in the shL1CAM group, but upregulated in the L1CAM overexpression group, as compared with the control." (PMID 33710805, 2021).
tumor (continued). "In addition to directly targeting malignant T cells, mogamulizumab depletes CCR4 + Tregs, which is an important therapeutic target in many human malignancies due to their role in suppressing the host anti-tumor immunity." (PMID 33384022, 2020). "In addition, CCR4+ CD30-directed CAR-T cell transfer resulted in superior antitumor activity in a xenotransplant model due to increased infiltration of T cells in the tumor." (PMID 32867162, 2020). "In melanoma, CCR4 was required for the homing of Tregs to nascent tumour sites from LNs." (PMID 32680511, 2020). "However, whereas NK cell-mediated ADCC was suggested as the major anti-tumor effector mechanism in humans, in mice not NK cells but rather myeloid cells seem to be responsible for the anti-CCR4 dependent tumor cell depletion." (PMID 32117269, 2020). "More specifically, anti-CCR4 mAb, among other effects, increased the numbers of infiltrating NK cells, suggesting that these may participate in tumor elimination following anti-CCR4 mAb administration." (PMID 32013092, 2020). "Animal studies on inoculated tumors, such as bladder cancer and renal cell carcinoma, showed the anti-tumor effects of mogamulizumab or Affi-5 (monoclonal antibodies targeting CCR4) which reduced the number of Treg and increased the number of NK cells and CD4+ T cells in the tumor." (PMID 33182504, 2020). "Since blocking of CCR4 could significantly reduce Tregs recruited in the tumor stage in a canine model, LAMP3+ DCs may also be a potential target for immune therapy." (PMID 33033240, 2020). "In addition to recruiting myeloid cells, the group also found that tumor- and TAM-secreted CCL2 can lead to the recruitment of Tregs through CCR4, further dampening the ability of CTLs to exert anti-tumor effect." (PMID 31396227, 2019). "Among the validated miR-135a cellular targets, CXCL2 is an antimicrobial gene serving as a ligand for the G-protein couple receptor CCR4 that plays a role in diverse cellular functions, including immune surveillance, inflammatory response, tissue homeostasis, and tumor growth and metastasis." (PMID 30456659, 2019). "A CCR4 antagonist is useful for alleviating immune suppression and preventing tumor growth." (PMID 30718772, 2019). "The CCR4 antibody can selectively suppress infiltration of tumor tissues by regulatory T cells." (PMID 31623180, 2019). "This study was designed to test the hypothesis that depletion of CCR4+ Tregs would enhance the effect of anti-tumor T cells expanded in response to a 4-1BB agonist." (PMID 31801624, 2019). "For instance, depletion of CCR4+ T cell types, such as memory, Th1, Th2, and resident memory T cells could impact the anti-tumor response elicited by combination therapy." (PMID 31801624, 2019). "The transience of the PR seen in a PD-1 refractory squamous NSCLC patient may be consistent with attenuation of anti-tumor activity mediated by CCR4-expressing T cells." (PMID 31801624, 2019). "The expression of CCL17/TARC and CCR4 may constitute an autocrine or paracrine survival loop which contributes to the growth and survival of the tumor, and also mediates immune suppression through the recruitment of regulatory T cells." (PMID 30140381, 2018). "The role of CCR4 in tumor growth and survival has previously been reported." (PMID 30140381, 2018). "CCR4 is a chemokine receptor expressed by tumor cells in about 90% of ATL patients." (PMID 29643841, 2018). "Furthermore, the recently developed anti-CCR4 humanized antibody mogamulizumab can rapidly eliminate CCR4+ ATL tumor cells." (PMID 29212930, 2018). "The fact that the tumor cells express CCR4 provides a therapeutic strategy for ATL." (PMID 29915722, 2018). "Moreover, humanized models proved instrumental in investigating the anti-tumor potential of anti-CCR4 antibodies." (PMID 29643841, 2018).
tumor (continued). "Importantly, mice inoculated with CCR4high expressing tumor cells and treated with a CCR4 antagonist had a significant reduction of primary tumor growth associated with a decrease of the presence of brain micrometastases." (PMID 30420855, 2018). "Possible differences in the expression pattern of CCR4 on tumor cells vs lymphocytes might be one of the reasons as CCL22 is reported to have higher affinity for CCR4-expressing lymphocytes." (PMID 28415693, 2017). "CCL17 was considered to attract CCR4+ Treg cells to the tumor." (PMID 28178948, 2017). "Tumor angiogenesis is a crucial aspect in the scenario of tumor growth and metastasis and, based on the data above, CCR4 could promote HCC tumor growth by facilitating blood vessel formation in vivo." (PMID 28959024, 2017). "The mechanism by which CCR4 promotes tumor growth in vivo still remains uncertain." (PMID 28959024, 2017). "For example, CCR4- expressing Tregs recruited to tumor sites may antagonize the anti- tumor activities of cytotoxic T cells thereby contributing to tumor growth." (PMID 28415693, 2017). "Moreover, primary tumors can induce the production of CCR4 ligands in the lungs of mice, which enable CCR4 positive tumor cells to migrate more easily." (PMID 27356745, 2016). "In addition, both a monoclonal antibody against human MCP-1 and a CCR4 antagonist significantly blocked tumor extract-induced aTreg cell migration (P < 0.01 for each)." (PMID 27177223, 2016). "We next examined the cytokine profiles of tumor-infiltrating lymphocytes following ex vivo stimulation, and found that T cells in the CCR4 antagonist-treated group secreted significantly higher amounts of IFN-γ, IL-2, and TNF-α than T cells in the control groups (P < 0.05 for each)." (PMID 27177223, 2016). "Considering that the immune microenvironment of tumor cells is so complex, however, there may be other factors could contribute the expression of CCR4." (PMID 27356745, 2016). "In vivo validation studies demonstrated that varying CNOT2 levels significantly influenced tumor metastatic capacity and implicated the CCR4-NOT complex as a novel determinant of tumor cell metastatic potential." (PMID 26807845, 2016). "Finally, we compared the expression of CCR4 on HNSCC tumor-infiltrating aTreg cells and matched circulating aTreg cells from 18 HNSCC patients." (PMID 27177223, 2016). "A significant association was observed between the CCR4 negative group and positive group in tumor size (P = 0.036), invasion depth (P = 0.020), lymphatic metastasis (P = 0.018), and TNM stage (P = 0.030)." (PMID 27356745, 2016). "A defucosylated anti-CC chemokine receptor 4 (CCR4), mogamulizumab, not only induces ADCC against CCR4+ malignant T cells but also reduces CCR4+ regulatory T cells (Tregs) which in turn restores NK cell anti-tumor function in patients with cutaneous T cell lymphoma (CTCL)." (PMID 27686492, 2016). "In addition, treatment of CNS tumor-bearing hosts with anti-CD25 mAb delayed the tumor growth and prolonged the survival, suggesting that CCR4+CD4+CD25+ Tregs play an important role in suppressing the immune response to CNS tumors." (PMID 26528477, 2015). "Through the release of CCL22/CCR4 and PGE2 or H-ferritin, tumor cells, including those in hematologic malignancies, cause attraction and expansion of Treg cells to the tumor site and in peripheral blood (PB), thereby increasing Treg cells in the tumor microenvironment and in PB." (PMID 25793623, 2015). "Although we observed a highly significant difference in proportions of Foxp3− and Foxp3+ T cells expressing CCR4 in spleens and lymph nodes, this difference was considerably reduced in the tumour where CCR4 was expressed on a high proportion of both Foxp3− and Foxp3+ T cells." (PMID 25495686, 2015).